BRCA2 (BRCA2 DNA repair associated)
Diseases named in the same sentence as BRCA2 in open-access papers (continued):
Sharing a sentence is not in itself a finding about the gene and the disease.
ovarian carcinoma (continued). "Therefore, the development of alternative approaches to target DNA repair is desirable in BRCA2-germline-mutated ovarian cancers." (PMID 37446144, 2023). "Women with pathogenic BRCA1 or BRCA2 variants are at high risk for breast and ovarian cancer." (PMID 37845719, 2023). "However, the most common and well-known examples are the pathogenic BRCA1 and BRCA2 genomic variants, present in 1 to 300–500 women and responsible for 5–10% of breast cancers, and 10–15% of ovarian cancers." (PMID 36826146, 2023). "Especially, BRCA1/BRCA2 mutation carriers have an increased risk for breast and ovarian cancer." (PMID 37781206, 2023). "Given that PARG suppression was indicated as one of the mechanisms of PARPi resistance in BRCA2-deficient cancer cells, we additionally explored the effect of TARG1 loss on PARGi sensitivity in BRCA2-deficient ovarian cancer PEO1 cells and observed a similar sensitivity phenotype." (PMID 37676774, 2023). "Notably, the majority of these mutations (56, representing 39.4%) was identified in the BRCA1/BRCA2 genes, primarily associated with breast (26.7%) and ovarian cancer (8.4%) syndromes." (PMID 38201513, 2023). "The BRCA2 gene is a well-known tumor suppressor gene implicated in breast and ovarian cancers." (PMID 37743480, 2023). "However, PVs not included in the routine screening were discovered with expected frequencies, in particular BRCA2 c.5286T>G, recently identified in Russian ovarian cancer patients as a new founder mutation." (PMID 37445679, 2023). "Women with inherited mutations in the BRCA1 or BRCA2 genes have increased lifetime risks for developing breast and/or ovarian cancer and may develop these cancers around the age of 30 years." (PMID 37365514, 2023). "About 15% of ovarian cancer patients have a germline mutation in the BRCA1 or BRCA2 genes, and in these cases, chemotherapy can be supplemented with the administration of PARP inhibitors, which limit the regeneration of the cells as well as the further growth and proliferation of the tumor cells." (PMID 36856946, 2023). "Mitoxantrone was selectively toxic in BRCA2-mutated ovarian cancer cells (PE01) in that study." (PMID 37446144, 2023). "For decades, hereditary breast and ovarian cancer (HBOC) has been attributed to PVs in the genes BRCA1 and BRCA2, and more recently other rare alleles have been firmly established as associated with a high or moderate increased risk of developing breast and/or ovarian cancer." (PMID 37563628, 2023). "Notably, transheterozygotes who have inherited deleterious mutations in both BRCA1 and BRCA2 were first reported in a Hungarian patient with breast/ovarian cancer." (PMID 37686625, 2023). "In Germany, women with newly identified BRCA1 or BRCA2 variants receive individual care and counseling on their genetic findings, cancer risks, and preventive options at the centers of the German Consortium of Familial Breast and Ovarian Cancer (GC-HBOC)." (PMID 37845719, 2023). "Mutations in BRCA1 and BRCA2 genes have been known for decades to predispose to familial breast and ovarian cancers, and, more recently, prostate and pancreatic cancers have been added to the constellation of cancers that show increased prevalence in these families." (PMID 36975505, 2023). "In this matched analysis of 430 women at a high risk of having ovarian cancer due to an inherited BRCA1 or BRCA2 mutation, we evaluated whether physical activity during adolescence and early-adulthood was associated with ovarian cancer." (PMID 38019076, 2023). "Certain germline mutations in BRCA1 and BRCA2 are known to increase the risk of ovarian cancer." (PMID 36981032, 2023). "BRCA deficiency was originally shown to result from coding mutations affecting the BRCA1 or BRCA2 genes, which are the principal determinants of genetic predisposition to breast and ovarian cancers and play central role in Homologous Recombination (HR) Repair, also called BRCA pathway." (PMID 37007122, 2023).
ovarian carcinoma (continued). "Genetic testing for pathogenic variants in BRCA1 and BRCA2 is widely available in breast and ovarian cancer, to enable not only early detection and risk reduction, but also to guide cancer treatment, e.g. consideration of the use of olaparib in chemotherapy regimens." (PMID 36927983, 2023). "To validate this hypothesis, in the current study, we evaluated MRE11 blockade as a synthetic lethality strategy in BRCA2-deficient ovarian cancers." (PMID 37446144, 2023). "For instance, survival rates vary significantly among different cancer types in CPG mutation carriers, with BRCA2-mutation-positive ovarian cancer patients experiencing significantly better outcomes and BRCA2-mutation-positive prostate cancer patients facing a less favorable prognosis." (PMID 37958970, 2023). "However, many of the currently available treatment options, such as PARP inhibitors veliparib and olaparib, are targeted agents for patients with BRCA1 and/or BRCA2 mutations and are therefore ineffective for many ovarian cancer patients." (PMID 36671544, 2023). "Screening for a diverse panel of BRCA1 and BRCA2 variants may be necessary to protect women in Arab populations who have a known family history of breast and/or ovarian cancer." (PMID 37306523, 2023). "We hypothesized that gBRCA1/BRCA2 carriers developing breast or ovarian cancer might be at higher risk for developing chemotherapy-related acute hematologic toxicity and therapy-related myeloid neoplasms." (PMID 37119509, 2023). "HRD has been observed not only in ovarian cancer patients with germline or somatic BRCA1 or BRCA2 mutations but also in those with epigenetic silencing of BRCA1 or loss of function of other genes, such as ATM, ATR, BARD, BRIP, EMSY, PALB2, RAD51, and Fanconi Anemia Complementation Group genes." (PMID 36836518, 2023). "However, women with pathogenic BRCA1 or BRCA2 mutations have a 55-72% and 45-69% chance of developing ovarian cancer by age 80, respectively." (PMID 37228496, 2023). "OVCAR8 cells are more resistant to PARPi because of their BRCA-proficient phenotype despite heterozygous methylation on the BRCA1 promoter, whereas PEO1 cells harbor a truncated BRCA2 mutation representing ovarian cancers deficient in DNA damage repair mechanisms." (PMID 36324587, 2022). "Germline pathogenic variants in BRCA1 and BRCA2 cause hereditary breast and ovarian cancer." (PMID 36068545, 2022). "A BRCA2 gene mutation was diagnosed in 7 (4.4%) unselected ovarian cancer cases." (PMID 35382848, 2022). "A BRCA1 or BRCA2 causative variant was found in 18 of 158 (11.4%) unselected ovarian cancer cases." (PMID 35382848, 2022). "Genetic counseling and testing for germline variants in BRCA1 and BRCA2 and in other hereditary breast and/or ovarian cancer (HBOC) susceptibility genes was established when the significance of hereditary cancer screening and preventive measures was recognized." (PMID 35326583, 2022). "Interestingly, we identified one uncommon c.5291C > G BRCA2 pathogenic mutation (p.Ser1764*) that has been previously reported in five Slovene hereditary breast and ovarian cancer families." (PMID 36672847, 2022). "Mutations in BRCA (BRCA1 and BRCA2) genes are also one of the major causes of ovarian cancers." (PMID 36415372, 2022). "Hereditary mutations in the BRCA1 and BRCA2 genes are risk factors for ovarian cancer." (PMID 35300046, 2022). "In particular women can be tested to search BRCA1 or BRCA2 unknown germline mutations, especially when suffering from breast and/or ovarian cancer, or to search known BRCA1/2 germline mutations previously identified in the family (i.e., cascade screening)." (PMID 35395021, 2022). "Regarding BRCA2, the cumulative risk for BC is 55% and for ovarian cancer is 17% at the age of 70." (PMID 35451682, 2022).
ovarian carcinoma (continued). "The NCCN recommends risk-reducing salpingo-oophorectomy (RRSO), typically between 35 and 40 years, and upon completion of childbearing in BRCA1 mutation, while it is reasonable to delay RRSO for management of ovarian cancer risk until age 40-45 years in patients with BRCA2." (PMID 35888662, 2022). "Women with BRCA1- or BRCA2-associated HCS have a lifetime risk of ovarian cancer between 17–44%." (PMID 35877228, 2022). "We showed, for the first time, a tremendously improved progression free survival time for 26% of PARPi treated epithelial ovarian cancer patients (with one to four preceding chemotherapy lines) with high corrected variant allele frequencies (cVAF) of either a BRCA1 or a BRCA2 mutation." (PMID 36143252, 2022). "Therefore, clearly both BRCA1 and BRCA2 are susceptible to mutations and play a large role in the pathogenesis of breast and ovarian cancer." (PMID 35740092, 2022). "Interestingly, BRCA1 and BRCA2 mutations are responsible for the development of about 90% of all ovarian cancers." (PMID 35740092, 2022). "However, BRCA2 variants are present amongst healthy individuals and only a subset are causative of hereditary breast and ovarian cancer." (PMID 35711920, 2022). "BRCA2 mutations lead to genome instability and increased risk of breast and ovarian cancer." (PMID 35053516, 2022). "Notably, the PEO1 cells are the first and only human BRCA2 defective ovarian cancer cell line identified thus far and, like the original patient, possess a BRCA2 hemizygous nonsense mutation 5193C > G (Y1655X)." (PMID 35964058, 2022). "Mutations in BRCA1 and BRCA2 genes are well-established risk factors of breast and ovarian cancer." (PMID 35382848, 2022). "A diagnostic finding that had clinical management implications beyond epilepsy care (secondary findings) was described in 3–4 % of individuals, for example a (likely) pathogenic variant in BRCA2 which is associated with a higher risk for breast and ovarian cancer." (PMID 38835877, 2022). "Carriers with BRCA2 pathogenic variants showed a later diagnosis of ovarian cancer (4.1 years)." (PMID 35420638, 2022). "In addition to breast and ovarian cancer, an increased risk for prostate cancer in BRCA2 PV carriers as well as pancreatic cancer in both male and female BRCA1/2 PV carriers has been recognized." (PMID 36497436, 2022). "Germline mutations in the BRCA1 and BRCA2 genes predispose persons to breast and ovarian cancer." (PMID 35918668, 2022). "Besides BRCA1 and BRCA2, several other inheritable mutations have been identified that increase ovarian cancer risk." (PMID 35159349, 2022). "More cases with BRCA1 reversion mutations were reported in ovarian cancer than BRCA2." (PMID 36557020, 2022). "Although the first approved PARPi (olaparib) initially targeted patients with ovarian cancer that carried germline mutations in the BRCA1 or BRCA2 genes, a later study demonstrated responses with olaparib in 41% and 24% of germline BRCA mutation carriers and non-carriers, respectively." (PMID 35203410, 2022). "Moreover, PEO1 cell line bears pathogenic BRCA2 mutation and therefore represents an OC tumour type defective for double stranded DNA repair, known to be associated with hereditary breast and ovarian cancer." (PMID 36333801, 2022). "The percentage of ovarian cancer [risk] is quite high if you are BRCA2 positive." (PMID 35887609, 2022). "Mutations in BRCA1 and BRCA2 account for up to 90% of familial breast and ovarian cancer cases." (PMID 36246618, 2022). "Furthermore, BRCA2 is known as a causative gene of hereditary breast and ovarian cancers, but mutant M784V has been reported to be neutral." (PMID 34984555, 2022).
ovarian carcinoma (continued). "Additionally, how to appropriately address the risk of ovarian cancer and fertility preservation arise as questions for this BRCA2 gene PV carrier." (PMID 36518309, 2022). "Moreover, as BRCA1/BRCA2 mutations are confirmed to be important high-risk factors for the development of ovarian cancer." (PMID 35991556, 2022). "In addition, the OC316 (heterozygous BRCA2 mutated) ovarian cancer xenograft model was used to extend results observed with SKOv3 and OVCAR8 xenografts." (PMID 35642638, 2022). "Moreover, BRCA1 and BRCA2 mutation carriers have risks of 60% and 55%, respectively, for developing ovarian cancer." (PMID 36140723, 2022). "The BRCA1 and BRCA2 genes are associated with hereditary breast and ovarian cancer." (PMID 35785170, 2022). "BRCA2 mutations specifically are associated with a 15–30% lifetime risk of ovarian cancer." (PMID 36230652, 2022). "The prevalence of germline BRCA1 or BRCA2 pathogenic variants (gBRCA1/2-PV) in patients with primary epithelial ovarian cancer (OC) in a rural area of Japan and their association with clinical characteristics, including treatment response and survival outcome, were investigated." (PMID 35741847, 2022). "BRCA1 and BRCA2 mutation carriers face an elevated lifetime risk of developing ovarian cancer." (PMID 35668475, 2022). "We highlighted the presence of specific mutational signatures (COSMIC signature 3) and genomic instability characteristics (LOH, TAI and LST), reflecting significant HRD, comparable with that observed in ovarian cancers with a BRCA1 or BRCA2 pathogenic variants." (PMID 35280729, 2022). "These mutations lie within the RAD51-binding domain (RAD51-BD) of the BRCA2 gene; ovarian cancer patients harboring mutations located at the RAD51-BD (exon 11) of the BRCA2 gene have prolonged survival compared to mutations occurring at other locations of the BRCA2 gene or to noncarriers." (PMID 34898566, 2021). "BRCA2 gene variants of unclear significance harbored by patients with breast and ovarian cancers." (PMID 34178674, 2021). "We hypothesized that FEN1 could be a promising alternative synthetic lethality target in BRCA2 deficient ovarian cancers." (PMID 33919707, 2021). "Mutations in BRCA1 and BRCA2 are well-established risk factors for breast and ovarian cancer." (PMID 33478551, 2021). "Moreover, WRN helicase inhibition markedly potentiated olaparib cytotoxicity in BRCA2-mutated ovarian cancer cells." (PMID 34772932, 2021). "Additionally, BRCA1 and BRCA2 are the most common genes associated with increased risk in hereditary breast and ovarian cancer." (PMID 34855882, 2021). "Further studies based on the NGS of BRCA1 and BRCA2 genes, as well as other genes that may be associated with a strong predisposition to ovarian cancer, should be carried on." (PMID 33478551, 2021). "Importantly, FEN1 inhibition was synthetically lethal in BRCA2 deficient or POLβ deficient ovarian cancer cells." (PMID 33919707, 2021). "Ovarian cancer screening in individuals with germline variants in BRCA1 or BRCA2 is contentious." (PMID 34771713, 2021). "The uterine and ovarian cancer association may be explained by either a mutation or an overexpression of BRCA1/BRCA2, and by MMR genes." (PMID 34556087, 2021). "BRCA2 c.658_659delGT mutation was detected in 2 ovarian cancer patients." (PMID 33478551, 2021). "Heritable mutations in BRCA1 and BRCA2 genes are a major risk factor for breast and ovarian cancer." (PMID 35008272, 2021). "Germline mutations of the BRCA1 and BRCA2 genes lead to a high lifetime risk of ovarian cancer." (PMID 34207450, 2021). "BRCA1 and BRCA2 genes have been constantly associated with breast and ovarian cancers." (PMID 33924591, 2021). "Hereditary breast and ovarian cancer is caused by a germline mutation in BRCA1 or BRCA2 genes." (PMID 34356066, 2021). "We hypothesised that polβ could be a promising alternative synthetic lethality target in BRCA2 deficient ovarian cancers." (PMID 33674744, 2021).
ovarian carcinoma (continued). "Additionally, stop codon variants of the BRCA2 gene are frequent among all pathogenic variants, leading to a significant increase in the risk of breast and ovarian cancer." (PMID 33672545, 2021). "Additionally, among ovarian cancer patients harboring BRCA2 mutations, most of them were located at exon 11 (11/16), affecting the RAD51-binding domain of the protein." (PMID 34898566, 2021). "PEO1, which is BRCA2 deficient, is a platinum sensitive ovarian cancer cell line." (PMID 33674744, 2021). "The c.7654dupA BRCA2 gene mutation which was identified in a unique family with a strong family history of breast and ovarian cancer is reported previously and exclusively in Algerian population and could be therefore specific to North African countries." (PMID 34490083, 2021). "Furthermore, this study demonstrated that patients with two inherited pathogenic variants were more likely to develop ovarian cancer compared with those with a BRCA2 pathogenic variant alone (16.9 vs. 9.3%, p = 0.0017)." (PMID 33507482, 2021). "Inherited mutation of either BRCA1 or BRCA2 is associated with familial breast and ovarian cancer." (PMID 34359565, 2021). "A BRCA1 or BRCA2 founder mutations were detected in 54 of the 214 (25.2%) ovarian cancer cases." (PMID 33478551, 2021). "BRCA2 biallelic pathogenic variants result in a severe form of Fanconi anemia (FA) syndrome, whereas monoallelic pathogenic variants cause mainly hereditary breast and ovarian cancer predisposition." (PMID 34504103, 2021). "Thus, to overcome past limitations, the goal of our study is to describe the punctual variants and copy number variations profile of BRCA1 and BRCA2 genes on Moroccan patients with breast and/or ovarian cancer suspected to have HBOC syndrome." (PMID 32778078, 2020). "Inherited mutations in BRCA2 predispose to breast and ovarian cancer." (PMID 32759814, 2020). "However, germline variants in other genes besides BRCA1 and BRCA2 are associated with ovarian cancer predisposition, which would be missed by a genetic testing aimed only at treatment decision." (PMID 33008098, 2020). "We hypothesized that BRCA2 (1342A>C) mutations are associated with the development of ovarian cancer in this family." (PMID 32356124, 2020). "BRCA1 and BRCA2 gene mutations account for 10~18% of ovarian cancer." (PMID 32356124, 2020). "Mutations in BRCA1 or BRCA2 are closely linked to familial breast and ovarian cancers." (PMID 31998560, 2020). "However, variants in other genes besides BRCA1 and BRCA2 are associated with ovarian cancer predisposition, which would be missed by a genetic testing aimed only at indication for PARP inhibitor treatment." (PMID 33008098, 2020). "Additionally, the use of PARP inhibitors with bevacizumab in clinical trials (NCT02354131) have shown an impressive preliminary disease control rate of 92% in 12 patients with BRCA2-mutated ovarian cancers." (PMID 32457830, 2020). "Similarly, it is estimated that women carrying harmful BRCA2 mutations have a 26 and 17% lifetime risk of inheriting breast and ovarian cancer, respectively." (PMID 33015058, 2020). "In summary, in this study, all female members of a typical HOC family were studied, and BRCA1 (3326A>T) and BRCA2 (1342A>C) mutations were detected, which may be the causative genes of ovarian cancer in this family." (PMID 32356124, 2020). "Thirdly, that any effect is limited to a subset of BRCA variants (e.g., the Ovarian Cancer Cluster Region which is associated with a much higher relative risk of ovarian cancer than other variants in BRCA1 or BRCA2) and that the variant profile differs in different cohorts." (PMID 31610093, 2020). "Furthermore, a BRCA2-mutated ovarian cancer cell line, with sensitivity to both platinum and PARPi, regained the BRCA2 function by secondary mutation after treatment with cisplatin and PARPi." (PMID 32316968, 2020).